MIR4677 (microRNA 4677)
Synonyms: hsa-mir-4677; mir-4677
Gene: MicroRNA gene on chromosome 1 (243,346,176 to 243,346,255, forward strand). Ensembl gene ENSG00000265201.
Homologues: Orthologues: chimpanzee MIR4677 (100% identical), macaque MIR4677 (100% identical).